EBAG9 (estrogen receptor binding site associated antigen 9)
Diseases named in the same sentence as EBAG9 in open-access papers (continued):
Sharing a sentence is not in itself a finding about the gene and the disease.
tumor (continued). "From these observations and from the detection of apoptotic tumor-infiltrating lymphocytes surrounding 22-1-1 mAb stained tumor lesions it was inferred that EBAG9 is a new death receptor ligand involved in tumor immune escape." (PMID 15904507, 2005). "To examine this possibility, we collected a confirmed list of immunosuppressive genes and found a positive correlation between p62 and the main suppressors of T-cell immune function on the tumor cell surface, including EBAG9, PVR, B7-H3, TNFRSF14, TGFB1, and PD-L1, in most cancers." (PMID 41291343, 2025). "Consequently, in Ebag9–/– CTLs, a profound advantage in allogeneic and tumor target cell lysis was obtained, in vitro and in vivo." (PMID 35482418, 2022). "Next, WT and Ebag9–/– mice were immunized with Co16.113 tumor cells." (PMID 35482418, 2022). "In the present study, applying an autochthonous tumor model, we found that enhanced cytolytic activity endowed Eμ-Tcl1 Ebag9–/– mice with a better clinical outcome compared with Eμ-Tcl1 Ebag9+/– mice, suggesting that immune escape can also be restored at the level of cytolytic capacity." (PMID 35482418, 2022). "With the continuous exploration of emerging immune checkpoints, TIM3, ARG1, and EBAG9 have been confirmed to exist in exosomes and may be involved in the regulation of tumor progression." (PMID 34743730, 2021). "PD-L1, CTLA-4, TIM3, ARG1, and EBAG9 have been confirmed to exist in exosomes and may be involved in the regulation of tumor progression." (PMID 34743730, 2021). "Considering that EBAG9 plays immune suppressive roles in both tumor and microenvironment, we here questioned whether EBAG9 is a transferable protein from cancer to surrounding T cells and affects antitumor immune response." (PMID 29362448, 2018). "We propose that the EBAG9 interactor TM9SF1 may cooperatively function in the EBAG9-mediated tumor-promoting effects." (PMID 29362448, 2018). "Here we questioned whether EBAG9 or cancer-derived EVs containing EBAG9 affect cancer cell biology, as well as immune surveillance system in tumor microenvironment." (PMID 29362448, 2018). "For instance, it has been suggested that the amplification of oncogenes on chromosome 8q (i.e., c-MYC and EBAG9) may support tumour progression." (PMID 18728668, 2008). "To investigate if expression of endogenous EBAG9 correlates with the occurrence of the 22-1-1 antigen, we have chosen several tumor cell lines and examined their EBAG9 protein content by immunoblot, whereas 22-1-1 surface staining was assessed by flow cytometry." (PMID 15904507, 2005). "Since we recently identified the O-linked glycan Tn as the antigen recognized by mAb 22-1-1, we asked whether the 22-1-1 defined antigen was tumor-specific, and whether this mAb recognizes the same antigenic structure as a monoclonal anti-EBAG9 antibody, Ab-1." (PMID 15904507, 2005). "Since many attempts are made to correlate mAb 22-1-1 reactivity and EBAG9 expression with clinical prognosis or even pathogenesis of tumors, these reports prompted us to revisit tumor-specificity of both antigens and their suggested role in induction of apoptosis." (PMID 15904507, 2005). "To test whether different endogenous protein expression levels of EBAG9 lead to surface display of the 22-1-1 antigen, we stained all tumor cell lines with mAb 22-1-1 and subjected them to flow cytometric analysis." (PMID 15904507, 2005). "Therefore, EBAG9 was introduced as a new death receptor ligand involved in tumor immune escape, reminiscent of the Fas/Fas ligand system." (PMID 15904507, 2005). "Applying immunohistochemistry on a representative selection of tumor and normal human tissue specimen, reactivity with the EBAG9-specific monoclonal antibody Ab-1, generated against a recombinant EBAG9 fusion protein, was seen in essentially all tissues and cell types examined." (PMID 15904507, 2005).
tumor (continued). "In addition to its autocrine functions in cancer cells, EBAG9 could behave as a new class of immune checkpoint that suppresses tumor immunity in a secretory manner." (PMID 29362448, 2018). "We first addressed the question whether EBAG9 is a tumor-specific marker." (PMID 15904507, 2005). "Tumor-derived sEV-mediated EBAG9 protein is a critical factor that promotes EMT of PCa cells while inhibiting cytotoxic T cells, thereby facilitating tumor progression." (PMID 38093355, 2023). "For EBAG9-silenced CAR T cells, the time required to achieve 50% of tumor cell killing was about 10 h shorter (median) compared with that of control BCMA CAR T cells." (PMID 35821635, 2022). "Collectively, EBAG9 silencing enhances effector capacity of TCR- and CAR-engineered T cells, results in improved tumor eradication, facilitates efficient manufacturing, and decreases the therapeutic dose." (PMID 35821635, 2022). "Other downregulated genes, such as HARS, UBXN1, EBAG9 and SGK1, reduce cytotoxic activity of T lymphocytes, block tumor T cell infiltration, drive T helper type 2 differentiation (TH2) or memory differentiation in CD8 T cells when expression is lost." (PMID 34654826, 2021). "EBAG9 has been found to be related to the pathophysiology of a variety of cancers, such as HCC, pancreatic cancer, and RCC, and has likewise been found to promote tumor progression and metastasis by inhibiting the cytotoxicity of immune cells." (PMID 34743730, 2021).
cancer (28 papers, 2001 to 2025). A tumor composed of atypical neoplastic, often pleomorphic cells that invade other tissues. "We have previously showed that estrogen receptor-binding fragment-associated antigen 9 (EBAG9) is a relevant cancer biomarker and facilities immune escape of cancers from the immune surveillance." (PMID 29362448, 2018). "EBAG9 stimulates the migration of cultured cancer cells and clinically associates with pathophysiology of various cancers including breast, ovarian, prostate, hepatocellular, renal, and bladder cancers." (PMID 29362448, 2018). "The findings reported herein demonstrate the considerably improved therapeutic potency and safety of EBAG9-silenced T cells and suggest their clinical application as a promising option for optimized cancer immunotherapy." (PMID 35821635, 2022). "Estrogen receptor-binding site-associated antigen (EBAG9, also referred to as RCAS1) is a tumor-associated antigen that is expressed at high frequency in a variety of cancers." (PMID 33227893, 2020). "As a result, we identified eight common mutated genes (EBAG9, MTDH, ATP6V1C1, OPA1, ATCL6A, BCL6, SENP5, KRAS) in the three different cancer types and used them as cross-cancer biomarkers to perform an integrative network analysis." (PMID 29459674, 2018). "This study showed that cancer-derived EVs contain EBAG9 protein, and proposed that EV-mediated EBAG9 transfer would contribute to cancer cell migration and immune escape." (PMID 29362448, 2018). "We demonstrated that EBAG9 protein is secreted in cancer-derived EVs, which are transferred to cancer cells and T cells, and function as a suppressor for T cell cytotoxicity." (PMID 29362448, 2018). "EBAG9 immunoreactivity was detected in the surface and cytoplasm of carcinoma cells in 46 out of 90 cases (51.1%)." (PMID 15164121, 2004). "We could speculate that the EBAG9-mediated glycosylation may modify unknown EMT-related proteins in cancer cells." (PMID 29362448, 2018). "We propose that EBAG9-targeting cancer treatment could be alternative therapeutic options for advanced diseases, particularly for those with EBAG9 overexpression." (PMID 29362448, 2018). "Upregulation of EBAG9 expression has been observed in several malignant tumors." (PMID 24992025, 2014). "Although the precise mechanism of immune evasion remains uncertain, the expression of EBAG9/RCAS1 may be a factor related to the escape mechanism of cancer cells from the host immune system." (PMID 15164121, 2004). "We questioned whether EBAG9 protein is secreted in EVs to influence cancer microenvironment." (PMID 29362448, 2018). "Results from our present study are consistent with these previous reports, and suggest that EBAG9 is widely distributed in carcinoma cells of human epithelial ovarian carcinoma tissues and cells, maybe especially in serous histology, as a result of oestrogen actions through ER." (PMID 15164121, 2004). "Our T cell population results are also in accordance with previous reports stating that RCAS1/EBAG9 was found in both membrane-bound and secreted forms in cancer." (PMID 37941832, 2023). "We identified TM9SF1 as a collaborative EBAG9 interactor, which regulates epithelial-mesenchymal transition (EMT) in cancer cells." (PMID 29362448, 2018). "Finally, we confirmed that the expression levels of the top immunosuppressive genes, EBAG9, PVR, TGFB1, B7-H3, TNFRSF14, and PD-L1, were significantly higher in the high-p62 group than in the low-p62 group in most cancers." (PMID 41291343, 2025). "While the mechanism of TM9SF1 remains to be elusive, we speculate that EBAG9 and TM9SF1 could cooperatively regulate cancer cell migration." (PMID 29362448, 2018). "For example, EBAG9, whose increased expression in CaP is a negative prognostic indicator, has a potential role in progression by enabling cancer cells to evade the immune response." (PMID 16573809, 2006). "EBAG9 is identical to RCAS1, a cancer cell surface antigen possibly involved in immune escape." (PMID 11742495, 2001).
hematologic malignancies (1 paper, 2022). "In view of the restricted cell biological effects of EBAG9, we consider it likely that EBAG9 downregulation is better suited to improve T cell targeting of hematologic malignancies." (PMID 35821635, 2022).
hematopoietic neoplasm (1 paper, 2022). "Hence, deleting Ebag9 in engineered T cells might be suitable for therapeutic exploitation, foremost in adoptive T cell transfer targeted at hematopoietic neoplasm." (PMID 35482418, 2022).
EBAG9 also shares sentences with these, for which no sentence is quoted: Hodgkins lymphoma (4 papers); ovarian endometriosis (4); endometrial cancer (3); nasal polyps (3); uterine cancer (3); adenocarcinoma (2); Colon Cancer (2); gallbladder cancer (2); hepatocellular carcinoma (2); squamous cell carcinoma (2); adenomyosis (1); B-cell lymphomas (1); breast tumors (1); cervical cancer (1); cholangiocarcinoma (1); chronic tonsillitis (1); colorectal cancer (1); cyst (1); diffuse large B-cell lymphoma (1); endometriosis (1); esophageal tumor (1); gastric carcinoma (1); head and neck cancer (1); hepatic cancer (1); immune dysfunction (1); inflammatory liver diseases (1); intrahepatic bile duct carcinoma (1); laryngeal carcinoma (1); laryngeal squamous cell carcinoma (1); lung carcinoma (1).
A further 15 diseases each share a sentence with EBAG9 in 1 paper.